TRIM32 (tripartite motif containing 32)
Description:
E3 ubiquitin ligase that plays a role in various biological processes including neural stem cell differentiation, innate immunity, inflammatory resonse and autophagy. Plays a role in virus-triggered induction of IFN-beta and TNF by mediating the ubiquitination of STING1. Mechanistically, targets STING1 for 'Lys-63'-linked ubiquitination which promotes the interaction of STING1 with TBK1. Regulates bacterial clearance and promotes autophagy in Mycobacterium tuberculosis-infected macrophages. Negatively regulates TLR3/4-mediated innate immune and inflammatory response by triggering the autophagic degradation of TICAM1 in an E3 activity-independent manner. Plays an essential role in oxidative stress induced cell death by inducing loss of transmembrane potential and enhancing mitochondrial reactive oxygen species (ROS) production during oxidative stress conditions. Ubiquitinates XIAP and targets it for proteasomal degradation. Ubiquitinates DTNBP1 (dysbindin) and promotes its degradation. May ubiquitinate BBS2. Ubiquitinates PIAS4/PIASY and promotes its degradation in keratinocytes treated with UVB and TNF (By similarity). Also acts as a regulator of autophagy by mediating formation of unanchored 'Lys-63'-linked polyubiquitin chains that activate ULK1: interaction with AMBRA1 is required for ULK1 activation. Positively regulates dendritic branching by promoting ubiquitination and subsequent degradation of the epigenetic factor CDYL. Under metabolic stress and phosphorylation by CHK2, mediates 'Lys-63'-linked ubiquitination of ATG7 at 'Lys-45' to initiate autophagy. (Microbial infection) May play a significant role in mediating the biological activity of the HIV-1 Tat protein in vivo. Binds specifically to the activation domain of HIV-1 Tat and can also interact with the HIV-2 and EIAV Tat proteins in vivo.
Synonyms: HT2A; TATIP; BBS11; LGMD2H; LGMDR8
Tractability: PROTAC: UniProt records ubiquitination sites on it; ubiquitination databases record sites on it; its protein half-life has been measured.
Gene: Protein-coding gene on chromosome 9 (116,687,305 to 116,701,300, forward strand). Ensembl gene ENSG00000119401.
Subcellular location: Cytoplasm; Mitochondrion; Endoplasmic reticulum
Subcellular location (Human Protein Atlas): Intermediate filaments
Pathways (Reactome):
Immune System: Antigen processing: Ubiquitination & Proteasome degradation; Regulation of innate immune responses to cytosolic DNA
Gene Ontology:
Molecular function: identical protein binding; protein binding; protein-macromolecule adaptor activity; transcription coactivator activity; ubiquitin binding; ubiquitin protein ligase activity; ubiquitin-protein transferase activity; myosin binding; RNA binding; Tat protein binding; translation initiation factor binding; zinc ion binding
Biological process: antiviral innate immune response; autophagosome assembly; cellular response to stress; free ubiquitin chain polymerization; innate immune response; negative regulation of cilium assembly; negative regulation of intrinsic apoptotic signaling pathway in response to DNA damage; negative regulation of toll-like receptor 4 signaling pathway; positive regulation of autophagosome assembly; positive regulation of autophagy; positive regulation of canonical NF-kappaB signal transduction; positive regulation of cell cycle; positive regulation of cell growth; positive regulation of cell migration; positive regulation of proteolysis; protein K48-linked ubiquitination; protein K63-linked ubiquitination; protein polyubiquitination; protein ubiquitination; response to oxidative stress; response to starvation; suppression of viral release by host; ubiquitin-dependent protein catabolic process; cellular response to amino acid starvation; fat cell differentiation; and 13 more
Cellular component: autophagosome; centrosome; cytoplasm; endoplasmic reticulum; mitochondrion; cytosol; nucleus; striated muscle myosin thick filament
Genetic constraint (gnomAD): Loss-of-function variants: 19 observed, 38.18 expected, observed/expected ratio (o/e) 0.5, 90% interval 0.35 to 0.73. The upper end of that interval is the gene's LOEUF score, 0.73, which puts it in group 2 of 6, group 1 being the genes least tolerant of losing a copy. Missense variants: 747 observed, 890.33 expected, observed/expected ratio (o/e) 0.84, 90% interval 0.79 to 0.89. Synonymous variants: 309 observed, 338.76 expected, observed/expected ratio (o/e) 0.91, 90% interval 0.83 to 1.
Gene-disease validity (ClinGen):
ClinGen rates the evidence that TRIM32 causes each of these diseases.
autosomal recessive limb-girdle muscular dystrophy (autosomal recessive): Definitive. Autosomal recessive form of limb-girdle muscular dystrophy.
Bardet-Biedl syndrome 11 (autosomal recessive): Limited.
Homologues: Orthologues: chimpanzee TRIM32 (99% identical), macaque TRIM32 (99% identical), dog TRIM32 (98% identical), guinea pig TRIM32 (98% identical), pig TRIM32 (97% identical), rabbit TRIM32 (97% identical), rat Trim32 (97% identical), mouse Trim32 (96% identical), zebrafish trim32 (64% identical). Paralogues in human: TRIM27 (14% identical), TRIM41 (14% identical), TRIM72 (13% identical), TRIML1 (13% identical), MID2 (13% identical), TRIM25 (13% identical), TRIM7 (13% identical), MID1 (13% identical), TRIM21 (13% identical), TRIM50 (13% identical), TRIM60 (13% identical), TRIM39 (13% identical), and 68 more.
Diseases named in the same sentence as TRIM32 in open-access papers:
TRIM32 is named in the same sentence as 120 diseases in open-access papers, as found by Europe PMC text mining. Sharing a sentence is not in itself a finding about the gene and the disease. The quoted sentences say what the papers report.
limb-girdle muscular dystrophy type 2H (14 papers, 2008 to 2025). "Limb-girdle muscular dystrophy autosomal recessive 8 (LGMDR8) is a rare clinical manifestation caused by the presence of biallelic variants in the TRIM32 gene." (PMID 38304327, 2024). "Mutations within the TRIM32 NHL domains cause the neuromuscular disease Limb-Girdle muscular dystrophy type 2H, whereas those within its BBOX domain result in the ciliopathic disorder Bardet-Biedl syndrome." (PMID 33277362, 2021). "For instance, mutated TRIM32 leads to limb-girdle muscular dystrophy type 2H; mutations in TRIM18 (MID1) cause Opitz G/BBB syndrome; and TRIM63/MuRF1 mutations result in hypertrophic cardiomyopathy." (PMID 25263070, 2014). "Limb girdle muscular dystrophy type 2H (LGMD2H) is an inherited autosomal recessive disease of skeletal muscle caused by a mutation in the TRIM32 gene." (PMID 22299041, 2012). "TRIM32 has been related to neuronal differentiation in mice and its deficiency (TRIM32 D487N mutation) is involved in Limb-Girdle muscular dystrophy type 2H (OMIM 254110)." (PMID 21798009, 2011). "It should also be noted that Trim32, found mutated in limb-girdle muscular dystrophy type 2H, is another putative E3-ubiquitin-ligase." (PMID 19015733, 2008). "However, mutations in TRIM32, such as those associated with limb-girdle muscular dystrophy type 2H (LGMD2H), impair its ability to activate p62." (PMID 39981097, 2025). "Moreover, TRIM32−/– mice also exhibited muscle weakness in both the hangwire test and traction test, which is probably due to limb-girdle muscular dystrophy type 2H caused by TRIM32 deficiency." (PMID 34421574, 2021). "Sarcotubular myopathy (STM) is a rare autosomal recessive myopathy caused by TRIM32 gene mutations." (PMID 33485293, 2021). "The TRIM32 knockout mouse, an animal model for limb-girdle muscular dystrophy type 2H, has shown a combination of myopathic and neuropathic changes." (PMID 39301689, 2024). "As an example, mutations in the gene coding for the RING- E3 ligase Tripartite motif-containing protein 32 (TRIM32) are associated with limb-girdle muscular dystrophy 2H (LGMD2H) and sarcotubular myopathy (STM)." (PMID 35127730, 2021). "A mutation in the B-box domain gives rise to Bardet–Biedl syndrome (BBS), a disease whose clinical presentation shares no muscle pathology, while mutations in the NHL (NCL-1, HT2A, LIN-41) repeats of TRIM32 causes limb-girdle muscular dystrophy type 2H (LGMD2H)." (PMID 33802079, 2021).
viral infection (14 papers, 2015 to 2025). "For example, the E3 ubiquitin ligases TRIM56 and TRIM32 catalyze the K63-linked ubiquitination of STING upon viral infection, thereby promoting STING recruitment and STING dimerization by TBK1." (PMID 35992663, 2022). "TRIM32 plays a role in regulating cellular processes beyond muscle cells and in the innate immune response to viral infections." (PMID 38225560, 2024). "A role of TRIM32 in the innate immunity has been reported in response to viral infection, as in the case of influenza and Herpes Simplex Viruses." (PMID 37543647, 2023). "Viral infections are detected by the innate immune system, and TRIM32 regulates innate immunity in response to both RNA and DNA virus infection by catalyzing the formation of the K63-linked ubiquitination of STING (also called MITA or TMEM173)." (PMID 37626915, 2023). "In mammals, tripartite motif 32 (TRIM32) is essential for regulating host innate immune responses to viral infections." (PMID 32184788, 2020). "These new findings suggest a possible important role of TRIM32 in host immune response against viral infection in fish." (PMID 27735853, 2016). "The TRIMs have been implicated in various antiviral effect and our results were in agreement with these previous findings and suggested that common carp TRIM32 also played a role in carp fish defense against viral infection or in brain development." (PMID 27735853, 2016). "We then determined the effect of TRIM32 on viral infection by examining IAV NP protein expression using Western blot and immunofluorescence." (PMID 26057645, 2015). "TRIM32 represents a model of intrinsic immunity, in which a host protein directly senses and counters viral infection in a species specific fashion by directly limiting viral replication." (PMID 26057645, 2015). "TRIM32 has also been shown to reduce the replication of spring viremia of carp virus, infectious hematopoietic necrosis virus, and white spot syndrome virus, suggesting that TRIM32 could be a potential immune enhancer of fish hosts for viral infection (66, –, 68)." (PMID 40793792, 2025). "To further investigate the potential mechanisms of TRIM32-mediated VEEV inhibition, we attempted to identify viral and cellular proteins that interact with TRIM32 during viral infection." (PMID 38895352, 2024). "The study found that TRIM32 upregulates NFKB, contributing to the regulation of the autophagic process in response to viral infection." (PMID 38225560, 2024). "HeLa-TRIM32 and HeLa-Fluc cells were infected with VEEV-nsP3/NLuc at MOI of 1, and cells were collected at multiple time points corresponding to steps of initial viral infection." (PMID 38895352, 2024). "In the absence of viral infection, endogenous TRIM32 is diffusely expressed in cytosolic foci and lesser amounts are detected in the nucleus." (PMID 26057645, 2015). "However, the functional link between 14-3-3η, TRIM32, and PB1 during viral infection remains unclear." (PMID 41157608, 2025). "However, we could not assess whether UPS inhibitors can subvert TRIM32-mediated inhibition of VEEV, because the host UPS also required for virus infection." (PMID 38895352, 2024).
limb-girdle muscular dystrophy (13 papers, 2011 to 2025). Limb-girdle muscular dystrophy (LGMD) is a heterogeneous group of muscular dystrophies characterized by proximal weakness affecting the pelvic and shoulder girdles. "TRIM3 has been implicated in the transport of cellular cargo, TRIM71 in microRNA and mRNA biology, and TRIM32 is thought to play a role in muscle filaments; mutations in TRIM32 are associated with limb-girdle muscular dystrophy." (PMID 30726215, 2019). "Additionally, we also found that Limb-girdle muscular dystrophy associated TRIM32 mutants R394H and D487N have a loss-of-function with respect to viral inhibition." (PMID 39527628, 2024). "Notably, we also show two TRIM32 pathogenic mutants R394H and D487N, related to Limb-girdle muscular dystrophy (LGMD), have a loss of antiviral activity against VEEV-TC83." (PMID 38895352, 2024). "Moreover, TRIM32 has been linked with certain disorders such as Bardet–Biedl syndrome (mutation in ‘the B-box’ domain of the gene), and limb-girdle muscular dystrophy (mutations in the ’C-terminal NHL domain’ of the gene)." (PMID 32121467, 2020). "TRIM32 mutants have been associated with LGMD-2H (limb girdle muscular dystrophy 2H)." (PMID 26884348, 2016). "Interestingly, this amino acid is mutated to malin-D233A in Lafora disease patients and TRIM32-D487N in Limb-Girdle muscular dystrophy patients." (PMID 21798009, 2011). "We additionally examined TRIM32 mutations associated with Bardet-Biedl syndrome (BBS11) and limb-girdle muscular dystrophies (LGMDs) affect anti-alphavirus activity." (PMID 38895352, 2024). "These genes are specifically associated with pathology in certain organs; for example, NPHP3 is associated with renal–hepatic–pancreatic dysplasia, BBS11/TRIM32 causes limb girdle muscular dystrophy, and KIF7 causes acrocallosal syndrome – none of these is considered a ciliopathy." (PMID 23351659, 2012). "Limb-girdle muscular dystrophy (LGMD) is a progressive muscle weakness affecting the pelvic and shoulder girdles, primarily caused by mutations in proteins like myotilin, lamin, caveolin-3, calpain-3, dysferlin, γ-sarcoglycan, TCAP, TRIM32, FKRP, and titin." (PMID 39415830, 2024). "There was no significant change in the expression level of tripartite motif-containing protein 32 (TRIM32) that controls myogenic differentiation via regulating c-Myc and is related to human limb-girdle muscular dystrophy 2 H36–38." (PMID 31844136, 2019).
gastric cancer (12 papers, 2018 to 2025). A primary or metastatic malignant neoplasm involving the stomach. "For instance, TRIM32, identified as a restriction factor against VEEV, is linked to poor survival in gastric cancer, possibly through its role in AKT phosphorylation and enhanced glucose transport in cancer cells." (PMID 40354393, 2025). "It has been shown that TRIM32 is highly expressed in gastric cancer, hepatocellular carcinoma, and CRC, and high expression is related to a poor prognosis." (PMID 40507857, 2025). "Studies have shown that when TRIM32 is silenced, the proliferation of gastric cancer cells is significantly inhibited and apoptosis is induced, which indicates that TRIM32 is directly involved in the regulation of the AKT pathway in gastric cancer cells." (PMID 40507857, 2025). "The silencing of TRIM32 can also effectively inhibit the tumorigenicity of gastric cancer cells in vivo, which highlights the potential value of TRIM32 in the treatment of gastric cancer." (PMID 40507857, 2025). "Multiple studies have demonstrated that the expression of TRIM32 is significantly up-regulated in breast cancer, gastric cancer, pancreatic cancer, and lung cancer." (PMID 40507857, 2025). "The knockdown of TRIM32 in gastric cancer cells, including NCI-N87, MKN74, and MKN45, resulted in increased apoptosis and decreased proliferation and AKT phosphorylation, which can be further enhanced by AKT inhibitors." (PMID 39768197, 2024). "The expression of TRIM32 is upregulated in several malignancies such as gastric cancer (GC), non-small-cell lung cancer (NSCLC), and hepatocellular carcinoma (HCC)." (PMID 35756612, 2022). "Jianjun Wang and colleagues identified a potential link between TRIM32 and Akt signaling in gastric cancer cells." (PMID 33802079, 2021). "However, the underlying function of TRIM32 in gastric cancer (GC) remains unclear." (PMID 32051827, 2020). "Recently, TRIM32 is reported to promote cell proliferation and invasion in gastric cancer by activating β-catenin signalling." (PMID 32051827, 2020). "TRIM32 plays an oncogene role in many cancers, including breast cancer, lung cancer, gastric cancer, and skin cancer." (PMID 33173411, 2020). "In gastric cancer (GC) cells, TRIM32 functions as a proliferation and anti-apoptosis factor." (PMID 40507857, 2025). "Collectively, these findings suggest that TRIM32 may drive gastric cancer cell proliferation by enhancing AKT activation and glucose transport." (PMID 40936722, 2025). "Similarly, TRIM32 was overexpressed in human gastric cancer tissues and cell lines (SGC7901 and AGS), correlating with increased levels of β-catenin." (PMID 39768197, 2024). "In gastric cancer cells, TRIM32 was able to promote the AKT activity and glucose transportation." (PMID 34921503, 2022). "TRIM32 upregulation poorly correlates with the overall survival of patients with gastric cancer." (PMID 33802079, 2021). "Moreover, TRIM32 is reported to exhibit tumor suppressor functions in many human cancers, including breast cancer, gastric cancer, lung cancer and skin cancer." (PMID 31820796, 2019). "In addition, TRIM32 can promote the proliferation and invasion of gastric cancer cell lines by activating β-catenin signaling pathway." (PMID 31820796, 2019). "Here, we aimed to investigate the role of TRIM32 in gastric cancer (GC) and the clinical implications." (PMID 30079558, 2018).
muscular dystrophy (10 papers, 2009 to 2023). Muscular dystrophy (MD) refers to a group of more than 30 genetic diseases characterized by progressive weakness and degeneration of the skeletal muscles that control movement. "Other genetic variants in the NHL repeats of TRIM32 have also been identified, and some of these variants lead to mild abnormalities in other organs as well as muscular dystrophies in skeletal muscle." (PMID 37626915, 2023). "Mutations in the RING domain of TRIM32 cause muscular dystrophy, but mutations in the BBS domain of the protein cause the developmental disorder Bardet-Biedl syndrome, indicating that the protein has diverse roles in CNS development and function." (PMID 33277362, 2021). "TRIM32 is an E3 ligase implicated in diverse biological pathways and pathologies such as muscular dystrophy and cancer." (PMID 33999923, 2021). "Since mutations in TRIM32 is associated with muscular dystrophy, similar experiment was performed in the myoblast C2C12 cell line." (PMID 33999923, 2021). "We studied three independent families of Spanish and Australian origin with a muscular dystrophy, and identified four novel TRIM32 mutations located in three different domains; NHL, coiled-coil and RING domains." (PMID 30823891, 2019). "We aimed to establish if patients with muscular dystrophy due to TRIM32 mutations show evidence for the pathogenic mechanism postulated in the mouse models." (PMID 30823891, 2019). "Our results demonstrate a common pathogenic pathway in the development of muscular dystrophy associated to TRIM32 mutations which lead to loss or reduction of the protein." (PMID 30823891, 2019). "TRIM32 KO muscles also show a decrease in the glycolytic proteins GAPDH and PyK, just as we observe a reduction in Ald and Pglym levels in tn-/- muscles, suggesting that TRIM32-mediated regulation of glycolysis may be a general mechanism that underlies some muscular dystrophies." (PMID 32223900, 2020). "In this study, we adopted an in vitro approach using recombinant point- and deletion-mutants to characterize the contribution of the TRIM32 Zn-binding domains to the activity of this E3 ligase that is altered in a genetic form of muscular dystrophy." (PMID 30884854, 2019). "An automated process has been developed for the detection of deletions, duplications/insertions and point mutations in any gene or family of genes and has been applied to ten genes known to bear mutations that cause muscular dystrophy: DMD; CAV3; CAPN3; FKRP; TRIM32; LMNA; SGCA; SGCB; SGCG; SGCD." (PMID 19835634, 2009).